PAK4 (p21 (RAC1) activated kinase 4)
Diseases named in the same sentence as PAK4 in open-access papers (continued):
Sharing a sentence is not in itself a finding about the gene and the disease.
pancreatic cancer (continued). "Inhibiting PAK4 or disrupting its connection with p85α reduces migration in pancreatic cancer cells." (PMID 38067120, 2023). "Inhibition of PAK4 not only reduces tumour growth but also enhances the efficacy of gemcitabine in mice carrying pancreatic cancer." (PMID 38067120, 2023). "PAK4/LIMK1 signaling mediates the chemoprotective action of CXCL12/CXCR4, and the inhibition of PAK4 leads to re-sensitization of pancreatic cancer cells to DTX-induced cellular toxicity even in the presence of CXCL12." (PMID 36230657, 2022). "Further, the knockdown of PAK4 in gemcitabine-resistant pancreatic cancer cells restores the cells’ sensitivity to the drug by upregulating hENT1 expression." (PMID 36230657, 2022). "Taken together, the preclinical studies proved that PF-3758309 is a potent druglike PAK4 inhibitor suitable for clinical trials for treating colon, leukemia, and pancreatic cancers with potentials to improve immune microenvironment." (PMID 36105226, 2022). "Dependent on the AKT and ERK signaling pathways, PAK4 in pancreatic cancer cells leads to cell proliferation and survival by promoting the nuclear accumulation of NF-κB." (PMID 36230657, 2022). "KPT-9274, as a selective and allosteric PAK4 inhibitor, significantly inhibits the proliferation of pancreatic cancer cells with preference over normal human ductal epithelial." (PMID 36105226, 2022). "In vitro studies have shown that inhibition of PAK4 with siRNA and other mechanisms, can reduce the growth of pancreatic cancer cells." (PMID 34944073, 2021). "Recently, Karyopharm Therapeutics (Newton, MA, USA) has made notable progress by identifying PAK4 allosteric modulators and has provided proof of concept for the treatment of pancreatic cancer in animal models." (PMID 30755582, 2019). "To examine substrate phosphorylation in an endogenous setting, we performed experiments in Panc1 pancreatic cancer cells that express PAK4 to high levels." (PMID 30897078, 2019). "The PAK4 gene is amplified in ~20% of patients with pancreatic cancer, and pancreatic tumors display increased PAK4 kinase activity." (PMID 30755582, 2019). "This will facilitate future use of our Pdx1-Cre-driven conditional PAK4 KO mouse model for testing in vivo potential functions of PAK4 in pancreatic disease models such as for pancreatitis and different pancreatic cancer forms." (PMID 28765528, 2017). "In pancreatic cancer cell lines stable PAK4 depletion led to a significant decrease in phosphorylated AKT levels." (PMID 27845911, 2017). "Further investigation revealed that reduced PAK4 expression in pancreatic cancer cells leads to a significant reduction in anchorage independent growth." (PMID 27845911, 2017). "Taken together our study supports further investigation of PAK4:PI3K signalling nexus in pancreatic cancer as a possible therapeutic target." (PMID 28205613, 2017). "p-21 activated kinase 4 (PAK4) is a gene that is recurrently amplified or overexpressed in PDAC and both PAK4 and related family member PAK1, have been linked to aberrant RAS activity, a common feature in pancreatic cancer." (PMID 27845911, 2017). "Of the PAK family members PAK4 was consistently expressed at higher levels in pancreatic cancer cell lines compared to normal controls." (PMID 28205613, 2017). "PAK1 and PAK4 have received the most attention because they are most frequently overexpressed; however, each of the five PAKs has been shown to be important in pancreatic cancer growth." (PMID 40001881, 2025). "RNAi knockdown of PAK4 increased tumor-suppressive miRNAs that regulate apoptosis and cell survival, and also enhanced apoptosis by disrupting PAK4’s phosphorylation of Bad in pancreatic cancer cells." (PMID 39337621, 2024). "Pancreatic cancer is treated by gemcitabine, and resistance to the drug is regulated by PAK4." (PMID 36830998, 2023). "Pancreatic cancer is often characterized by mutant KRAS mutation, and PAK4 is amplified in PDAC." (PMID 36830998, 2023).
pancreatic cancer (continued). "It has been reported that p21-activated kinase 4 (PAK4) is amplified in pancreatic cancer tissue." (PMID 28205613, 2017). "Having established that PAK4 is expressed in pancreatic cancer cells and that those cells with high expression of PAK4 also have a migratory response to HGF we sought to establish whether PAK4 expression was required for the migratory response to HGF." (PMID 28205613, 2017). "This mouse model may therefore be used to test the potential in vivo functions of PAK4 in pancreas disease models, such as for pancreatitis and different pancreas cancer forms." (PMID 28765528, 2017). "Importantly, we also detect an interaction between PAK4 and endogenous p85α in the pancreatic cancer cells." (PMID 28205613, 2017). "Importantly, PAK4 is overexpressed in a range of pancreatic cancer cell lines (including PaTu8988T), which correlates with an increased expression of c-Met, K-ras and the p85α subunit of PI3K." (PMID 28205613, 2017). "Genomic amplification of PAK4 is reported in ovarian and pancreatic cancers." (PMID 27542207, 2016). "Recently, PAK4 has been indicated to enhance the survival and decrease the apoptosis of prostate cancer cells following chemotherapy, and to be a predictive marker of gemcitabine sensitivity in pancreatic cancer cell lines." (PMID 26411419, 2015). "PAK4 gene is localized at chromosome 19q13, a region amplified in pancreatic tumor specimens." (PMID 25238288, 2014). "Furthermore, because PAK2 and PAK4 have been related to pancreatic cancer, these two p21-activated kinases could be considered a prognostic and immunotherapeutic marker pancreatic cancer; therefore, future research in this direction should be necessary." (PMID 40001881, 2025). "Additionally, pancreatic cancer progression could also be restrained by other types of engineered exosomes, such as PCCs-derived Exosomes loading with short interfering RNA against P21-activated kinase 4 (PAK4), and BM-MSCs loading with miR-1231." (PMID 39054529, 2024). "Therefore, PAK4 has been proposed a pivotal target for pancreatic carcinoma." (PMID 36105226, 2022). "It has been established that PAK4 may be a driver of pancreatic cancer cell migration." (PMID 28205613, 2017). "P21-activated kinase 4 (PAK4) was found to be oncogenic, and the encapsulating si-PAK4 in PANC-1 cell-derived exosomes successfully suppressed pancreatic tumors in vitro and in vivo." (PMID 40432919, 2025). "In pancreatic cancer, all three group I PAKs (PAK1–3), as well as each of group II PAKs (PAK4–5), except for PAK6, have been reported." (PMID 40001881, 2025). "In this context, our analysis of RNA-sequencing data from the human pancreatic cancer cell lines PANC1 and MIAPACA2 treated with a designed G4 ligand CM03 revealed downregulation of PAK1, PAK2, PAK4, and PAK6 mRNAs." (PMID 36830998, 2023). "GCB in combination with gemcitabine has also been reported to reduce the growth of pancreatic cancer cells through the down-regulation of PAK1 and PAK4." (PMID 33567682, 2021). "PAK4, a dual Cdc42/Rac1 effector, is overexpressed in pancreatic CSCs and functions as an upstream activator of STAT3, which is required for pancreatic cancer stemness." (PMID 32915198, 2020). "Our data suggests that both PAK4 and PI3K are essential components of the migratory response of pancreatic cancer cells to HGF both in 2D and 3D." (PMID 28205613, 2017). "The p21-activated kinase 4 (PAK4) gene is amplified on the chromosome19q13, a region found frequently amplified in pancreatic cancer." (PMID 28383487, 2017). "However, how PAK4 may drive pancreatic cancer cell invasion has yet to be fully elucidated." (PMID 28205613, 2017). "Our data suggests that both PAK4 and PI3K have functionality during the migration of pancreatic cancer cells in the presence of HGF." (PMID 28205613, 2017).
pancreatic cancer (continued). "Next, we also examined the expression of PAK4 in pancreatic cancer progression (hTERT-HPNE and derived cell lines) model to correlate the expression of PAK4 with progression of pancreatic cancer." (PMID 25238288, 2014). "PAK signalling influences endothelial behaviour and immune functions; however, the specific roles of PAK1 or PAK4 in vascular reprogramming, hypoxia, and the gemcitabine response have not been fully addressed in pancreatic cancer." (PMID 41294859, 2025). "PAK1 and PAK4 double knockout (PAK1&4KO) suppressed pancreatic tumour volume in a SCID mouse model, but not tumour weight, suggesting that PAK4KO-induced increased tumour weight compromised PAK1KO-reduced tumour weight." (PMID 41228228, 2025). "Pancreatic cancer: PAK1 and PAK4 are known to be overexpressed in pancreatic cancer." (PMID 36830998, 2023). "However, the functionality of PAK4 in pancreatic cancer and the contribution made by HGF signalling to pancreatic cancer cell motility remain to be elucidated." (PMID 28205613, 2017). "Furthermore, in numerous normal and tumor cells with various stimuli, PAK4 activation mediates ERK1/2 stimulation, including in pancreatic cancer cells, in gastric cancer cells and in A549 human lung cancer cells, as well as stimulating the Mek1/2 cascade in gastric cancer cells and other tissues." (PMID 40001881, 2025). "Interestingly, in pancreatic cancer, PAK4 exhibited the highest frequency of alterations (10%), a notable increase compared to PAK2 (4%) and PAK3 (1%), while PAK1, PAK5, and PAK6 were altered in fewer than 1% of cases." (PMID 39756822, 2025).
gastric cancer (30 papers, 2014 to 2025). A primary or metastatic malignant neoplasm involving the stomach. "Consistently, a higher expression of PAK4 was associated with poor prognosis in various cancers, including breast, lung, ovarian, and gastric cancer." (PMID 36980457, 2023). "RCC2, together with PAK4, were co-immunoprecipitated with CORO1C, whereas knockdown of PAK4 ceased the association of CORO1C with RCC2 in gastric cancer cells." (PMID 35593474, 2022). "Moreover, high PAK4 levels are associated with chemoresistance in gastric cancer, ovarian cancer, and pancreatic ductal adenocarcinoma." (PMID 38238316, 2024). "Its efficacy lies in the effective suppression of SGC7901 gastric cancer cell invasion by attenuating the phosphorylation levels of PAK4 and its downstream effector, SCG10." (PMID 40332759, 2025). "This latter finding differs from the findings in gastric cancer, wherein PAK4 is an important regulator of the activation of the PI3K pathway." (PMID 40001881, 2025). "LCH-7749944, possessing moderate potency, acts as an inhibitor targeting PAK4, exerting its inhibitory prowess on the migration and proliferation of human gastric cancer cells." (PMID 40332759, 2025). "GL-1196 and LC-0882 are both small-molecule inhibitors of PAK4, both of which inhibit the phosphorylation of PAK4, and inhibit the G1/S transition of the gastric cancer cells by downregulating Cyclin D1." (PMID 40332759, 2025). "PAK4 confers cisplatin resistance in gastric cancer cells via PI3K/AKT and MEK/ERK-dependent pathways." (PMID 38238316, 2024). "Higher PAK4 expression was significantly related to advanced tumor stage, lymph node metastasis, and shorter survival of gastric carcinoma patients." (PMID 36980457, 2023). "In gastric carcinoma tissue, PAK4 was mainly expressed in the cytoplasm of tumor cells and a higher expression of c-PAK4 predicted shorter survival for gastric carcinoma patients." (PMID 36980457, 2023). "At concentrations of higher than 20 μm, this compound effectively suppressed phosphorylation of PAK4 and the proliferation of human gastric cancer cells through downregulation of both PAK4/c-Src/EGFR/cyclinD1 signaling and CDK4/6 expression." (PMID 36105226, 2022). "It was found that PAK4 co-localized with GEF-H1, and PAK4S99A showed obvious association with microtubules compared with PAK4S99D in gastric cancer cells." (PMID 35593474, 2022). "Our results reveal a new mechanism by which PAK4 regulates the migration potential of gastric cancer cells through microtubule-microfilament cross talk." (PMID 35593474, 2022). "PAK4 plays an important role in the occurrence and development of gastric cancer, especially in the process of invasion and metastasis." (PMID 35593474, 2022). "All these data suggest that the phosphorylation state of the Ser99 residue of PAK4 regulates the distribution of PAK4 in gastric cancer cells as well as the migration of gastric cancer cells." (PMID 35593474, 2022). "It was also identified to be a necessary region both for the leaing edge localization of PAK4 and for PAK4/CORO1C-induced migration of gastric cancer cells." (PMID 35593474, 2022). "We confirmed the interaction of CORO1C with PAK4 and found the colocalization of CORO1C with PAK4 on the membrane of gastric cancer cells." (PMID 35593474, 2022). "Here we discover that CORO1C, a member of coronin family that regulates microfilament and lamellipodia formation, recruits cytoplasmic PAK4 to the leading edge of gastric cancer cells by C-terminal extension (CE) domain of CORO1C (353–457 aa)." (PMID 35593474, 2022). "MiR-199a/b-3p inhibits gastric cancer cell proliferation via downregulating the PAK4 (p21 activated kinase 4)/MEK (mitogen-activated protein kinase kinase)/MAPK (mitogen-activated protein kinase 1) signaling pathway." (PMID 31754335, 2019).
gastric cancer (continued). "A study of cisplatin resistant (CDDP) gastric cancer cells also confirmed that in PAK4 SiRNA depleted cells there is a reduction in phosphorylated AKT, whilst total AKT levels were unchanged." (PMID 27845911, 2017). "Elevated levels of PAK4 have been examined in multiple types of cancer that include colorectal, ovarian, mammary, and gastric cancers." (PMID 28680855, 2017). "Given its broad involvement in cellular process, it is well established that PAK4 plays an important role in the tumorigenesis and progression of several kinds of cancers, particularly gastric cancer." (PMID 27077843, 2016). "More importantly, we identify this novel small molecular compound suppressing human gastric cancer cells via targeting PAK4, and provide a potential therapeutic strategy for gastric cancer by blockade of PAK4 signaling." (PMID 27077843, 2016). "More importantly, PAK4 was recently reported to be overexpressed in metastatic gastric cancer patients, and the high level of activated PAK4 correlates with poor prognosis." (PMID 27077843, 2016). "Our results showed that GL-1196 effectively suppressed the invasive capability of gastric cancer cells in conjunction with downregulation of PAK4/LIMK1/cofilin pathway, much as previously revealed in prostate cancer cells." (PMID 27077843, 2016). "In this paper, we reported that GL-1196, as a small molecular compound, effectively suppressed the proliferation of human gastric cancer cells through downregulation of PAK4/c-Src/EGFR/cyclinD1 pathway and CDK4/6 expression." (PMID 27077843, 2016). "And in gastric cancer, overexpressed PAK4 has also been suggested to confer the resistance to capecitabine/cisplatin chemotherapy." (PMID 26411419, 2015). "This would be of great interest, since one study described that application of LCH-7749944, an inhibitor of p21-activated kinase 4, inhibits migration and invasion of gastric cancer cells through inhibition of the PAK4/LIMK1/Cofilin signaling cascade." (PMID 26345720, 2015). "In this study, we found that PAK4 induces CDDP resistance in gastric cancer cells, mainly through activation of PI3K/Akt and MEK/ERK pathways." (PMID 27919028, 2014). "PAK4 was found to be overexpressed in metastatic gastric cancer patients, implicating a role of PAK4 in gastric cancer metastasis." (PMID 27919028, 2014). "It will be important to determine the effect of PAK4 on CDDP resistance in gastric cancer cells in vivo." (PMID 27919028, 2014). "In this study, we found that PAK4 (p21-activated kinase 4) expression and activity were elevated in gastric cancer cells with acquired CDDP resistance (AGS/CDDP and MKN-45/CDDP) compared with their parental cells." (PMID 27919028, 2014). "Next, we used the PAK4 inhibitor PF-3758309 to determine the role of PAK4 in CDDP resistance in gastric cancer cells." (PMID 27919028, 2014). "p21-activated kinase 4 (PAK4) induces CDDP resistance in gastric carcinoma cells by activation of the MEK/Erk and PI3K/Akt pathways." (PMID 25003395, 2014). "Many preclinical and clinical studies have reported that overexpression or genomic amplification of PAK1, PAK2, and PAK4 is often detected in multiple tumor tissues, including pancreatic, ovarian, breast, and gastric cancers, warranting these three isoforms as potential targets for cancer treatment." (PMID 36105226, 2022). "The overexpression of PAK4 is reported to be closely related to the occurrence and development of various cancers, including pancreatic, breast, ovarian, and gastric cancers." (PMID 34912075, 2022). "To evaluate the contribution of Ser99 residue to the distribution of PAK4 in cells and to the migration of gastric cancer cells, we constructed two PAK4 mutants: PAK4S99A (Ser to Ala) that cannot be phosphorylated and PAK4S99D (Ser to Asp) that mimic the phosphorylation state." (PMID 35593474, 2022). "This promoted us to study the association of PAK4 with GEF-H1 and Tctex-1 in gastric cancer cells." (PMID 35593474, 2022).